GZMB (granzyme B)
Diseases named in the same sentence as GZMB in open-access papers (continued):
Sharing a sentence is not in itself a finding about the gene and the disease.
HIV-1 infection (11 papers, 2011 to 2025). The type species of lentivirus and the etiologic agent of acquired immunodeficiency syndrome (AIDS). "Granzyme B-positive MAIT cells were detected during acute HIV-1 infection (PHI), up to 10-fold higher than HIV-1- controls." (PMID 34951583, 2021). "Taken together, these data indicate that chronic HIV-1 infection drives the expansion of CD56neg NK cells that express lower levels of granzyme B and perforin and display defective production of cytokines, such as IFN-γ and TNF-α." (PMID 35069597, 2021). "Activation-induced inhibitory receptors PD-1 and TIM-3 followed a similar pattern of expression to granzyme B during acute and chronic HIV-1 infection." (PMID 34951583, 2021). "Intriguingly, ex vivo neutralization of miR-146a in PBMCs from chronic HIV-1 infection exhibited an elevated antiviral cytokines production as well as the expression of GZMB and perforin, while simultaneously, decreased the inhibitory receptors expression such as PD-1, CTLA-4, TIM-3 and LAG-3." (PMID 31827152, 2019). "(A) Representative histograms showing upregulation of the activation/inhibitory markers PD-1, Granzyme B (GzmB) and TIM-3 in MAIT cells in chronic HIV-1 infection (CHI) compared to a healthy control (HC)." (PMID 34951583, 2021). "Furthermore, it has been reported that both CD4+ cytotoxic T lymphocytes (CTLs) and CD8+ CTLs expressing GNLY, GZMB, PRF proteins exhibit antimicrobial activity against intracellular bacteria and in HIV-1 infection." (PMID 40264781, 2025). "The proportion of perforin and granzyme B-positive NK cells was high in uninfected mice, and HIV-1 infection did not significantly increase that proportion." (PMID 36851579, 2023).
non-small cell lung carcinoma (11 papers, 2021 to 2025). A group of at least three distinct histological types of lung cancer, including non-small cell squamous cell carcinoma, adenocarcinoma, and large cell carcinoma. "Increased expression of GZMB was connected with high numbers of mutations in non-small-cell lung cancer." (PMID 35432539, 2022). "For example, SCS was performed on patients with non-small cell lung cancer (NSCLC), which identified 12 key genes including MS4A1, CCL5, and GZMB as potential diagnostic and prognostic biomarkers." (PMID 41340965, 2025). "Furthermore, in patients with stage IV non-small cell lung cancer who were treated with ICIs, high levels of GZMB resulted in better OS and PFS." (PMID 35846123, 2022). "In addition, the research on T-cell showed that co-expression of PD-1, LAG-3 and TIM-3 was associated with prominent activation (CD69 expression) and effector function (GZMB level), as well as elevated levels of proapoptotic markers in non-small cell lung cancer." (PMID 39767624, 2024). "A recent study reported that non-small cell lung cancer showing a complete pathological response to immunotherapy exhibits a stronger immune infiltrate, characterized by higher levels of IFNG, GZMB, NKG7, and M1 macrophages." (PMID 39888994, 2025).
ZIKV infection (11 papers, 2017 to 2025). "ZIKV activation of CD8 T cells has been associated with significant IFN gamma, TNF alpha, and granzyme B production (88, –, 90), all of which are cytotoxic, despite being required to control ZIKV infection." (PMID 40401980, 2025). "In this model, ZIKV infection caused an increased frequency of activated CD8 T cells in the spleen, which were shown to be positive for granzyme B." (PMID 31382545, 2019). "Furthermore, CD8 T cells upregulate expression of IFN-γ and TNF-α, produce the cytolytic molecule granzyme B, and present a highly activated phenotype following ZIKV infection." (PMID 31382545, 2019). "Others have shown that Granzyme B levels in CD4+ and CD8+ T cells peaked between 7 and 10 days post-ZIKV infection." (PMID 32463814, 2020). "During acute ZIKV infection, expanded Vδ2 T-cells were previously shown to produce IFN-γ and express granzyme B, suggesting a potential cytotoxic capability in the first phases of ZIKV infection." (PMID 31547470, 2019). "In addition, KLRG1+ CD8+ effector T cells and effector memory T cells as well as CD8+ T cells expressing granzyme B, interleukin 2 (IL-2) and IFN-γ were more frequently detected in B6 mice following ZIKV infection, indicating the activation of CD8+ T cell response in vivo." (PMID 40920828, 2025). "Our group and others have demonstrated that ZIKV infection in immunocompetent mice can lead to induction of CD8 T cell immunity, featuring the production of key effector cytokines such as IFN-γ or TNF-α, and the cytolytic molecule granzyme B, suggesting they are important for ZIKV immunity." (PMID 34193875, 2021). "Similarly, higher numbers of CD8+ T cells expressing granzyme B were present in DENV-immune compared to non-immune dams after ZIKV infection." (PMID 30072692, 2018). "Additionally, we established that cross-reactive DENV antibodies enhance ZIKV infection in KU812 cells, which is selectively coupled to enhanced chemokine ligand 5 (CCL5), interleukin 1β (IL-1β), and C-X-C motif chemokine ligand 10 (CXCL10) secretion and inhibited granzyme B (GrB) secretion." (PMID 35862953, 2022). "Upon polyclonal stimulation ZIKV infection triggered an expansion of CD8+ T cells expressing IL-2, CD107a, Granzyme B and Perforin, but not IFNγ." (PMID 30087337, 2018).
dengue (10 papers, 2015 to 2025). "We have demonstrated that NK cell cytotoxic dysfunction (lower expression of perforin and granzyme B) is associated with more severe dengue disease and may underly the hyperinflammatory/MAS phenotype." (PMID 35267010, 2022). "We have shown that patients with severe dengue have a lower percentage of activated and proliferating NK cells and lower expression of the cytotoxic granules perforin and granzyme B when compared to patients with less severe dengue infection." (PMID 39931105, 2024). "We therefore analysed Granzyme B function in acute dengue and found this followed the same time course as that of CD38." (PMID 27337592, 2016). "However, we found that while DENV-NS3 specific T cells of those with past mild/sub clinical dengue infection were more likely to produce only granzyme B, those who were hospitalized due to dengue were more likely to have DENV-NS3-specific T cells that produce TNFα and IFNγ or TNFα alone." (PMID 25875020, 2015). "We used the KU812 cell line to demonstrate for the first time that anti-dengue antibodies enhanced infectious Zika virus replication in a mast cell model and specifically increased CCL5, CXCL10, and IL-1β, while also impairing granzyme B secretion." (PMID 35862953, 2022). "Conversely, GzmB expression in CD8+ T-cells negatively correlates with plasma leakage and endothelial dysfunction, suggesting a protective role of cytotoxic CD8+ T-cells in dengue." (PMID 40595657, 2025).
endometriosis (10 papers, 2019 to 2025). The growth of functional endometrial tissue in anatomic sites outside the uterine body. "Targeting GZMB might alleviate endometriosis-associated pain and inflammation while preserving fertility." (PMID 37662927, 2023). "IL6 suppresses the cytolytic activity of NK cells in the peritoneal fluid of patients with endometriosis, concomitantly downregulating NK cells’ cytolytic molecules (e.g., granzyme B and perforin)." (PMID 37570749, 2023). "GZMB is a therapeutic target for endometriosis, based on its role in immune response, tissue remodeling, and angiogenesis." (PMID 37662927, 2023). "Regarding the mechanisms of low PBMC cytotoxicity in patients with endometriosis, the toxic granules (granzyme B, perforin, and granulysin) and surface receptors (NKG2D, NKp30, NKp46, CD158a, and CD158b) of peripheral NK cells were analyzed." (PMID 34531861, 2021). "Granzyme B and perforin secretion were reduced in NK cells from endometriosis patients." (PMID 40508002, 2025). "The outcomes from that paper were that some immune cells, including F4/80- and CD11c-positive macrophages, granzyme B-positive NK cells/cytotoxic T lymphocytes, and IL-17–positive Th-17 cells, contribute to the pathogenesis of endometriosis by increasing the secretion of proinflammatory cytokines." (PMID 37143676, 2023). "IL-6 or peritoneal fluid from endometriosis patients reduces the cytolytic activity of NK cells, concomitantly with the down-regulation of granzyme B, perforin, and the killer activating receptor (NKp46), while increasing the killer inhibitory receptor (CD158b)." (PMID 34531861, 2021). "Interestingly, the levels of NK cell cytotoxic granules such as granzyme B, perforin, and CD107a were decreased in the peritoneal fluid of women with endometriosis." (PMID 34616540, 2021). "We found that the gene expression of GZMB was significantly down-regulated (0.546 ± 0.079 vs. 1.300 ± 0.278, P = 0.0149) while XCL1 was up-regulated (3.889 ± 0.466 vs. 1.672 ± 0.238, P = 0.0006) in endometriosis compared to that of control groups." (PMID 34039410, 2021). "The highly differential genes between the two groups showed that C–C motif chemokine ligand 3 (CCL3) and X-C motif chemokine ligand 1 (XCL1) were significantly elevated in endometriosis while cytotoxic molecules including GNLY, GZMB and GZMH were significantly down-regulated." (PMID 34039410, 2021).
metastatic melanoma (10 papers, 2017 to 2025). A melanoma that has spread from its primary site to another anatomic site. "Our data shows that granzyme B degraded type IV collagen (C4G) associates with favorable anti-CTLA-4 treatment response in metastatic melanoma patients." (PMID 32998446, 2020). "Interestingly, granzyme B-degraded type IV collagen fragments (C4G) associate with favorable anti-CTLA-4 treatment response in metastatic melanoma patients." (PMID 34121658, 2021). "By evaluating NK cells in the blood of CM patients, it was discovered that NK cells entering metastatic melanoma tissue have a diminished cytotoxic capacity due to decreased expression of GZMB and perforin." (PMID 35957907, 2022). "Our findings show that a biomarker measuring granzyme B degraded type IV collagen (C4G) is predictive for response to anti-CTLA-4 therapy in metastatic melanoma patients." (PMID 32998446, 2020). "By developing a technically robust assay, we identified and quantified granzyme B-mediated type IV collagen degradation fragments (C4G) in the circulation of metastatic melanoma patients." (PMID 32998446, 2020). "In this study, we evaluated the biomarker potential of measuring granzyme B-mediated degradation of type IV collagen (C4G) in combination with a fibroblast activation biomarker (PRO-C3) non-invasively for identifying metastatic melanoma patients responding to the ICI ipilimumab." (PMID 32998446, 2020). "For example, metastatic melanoma cells could cannibalize live T lymphocytes as a way to feed, Natural killer (NK) cells inside tumor cells may die in an apoptotic way, likely due to reuptake of the released granzyme B (GZMB), for tumor cell survival." (PMID 35436988, 2022). "In metastatic melanoma patients, responders to anti‐PD‐1 ICIs exhibited significantly higher densities of intra‐ and peritumoural CD16+ and granzyme B+ NK cells." (PMID 39715697, 2025). "Granzyme B+ and T-CD4+ were examined by IHC in the lung nodules of metastatic melanoma treated with Rb9." (PMID 32010152, 2019).
Allergy (9 papers, 2012 to 2024). An allergy is an immune response or reaction to substances that are usually not harmful. "Our prior study showed that cytotoxic CD8+ Treg cells increasing expression of granzyme B may induce apoptosis of CD4+CD45RO+ memory T cells during allergy immunotherapy." (PMID 24475019, 2014). "While steady-state dietary signals promoted Granzyme B expression in Tregs, we showed that incoming Tregs in the allergy model further upregulated Granzyme B, whereas tolerant mice suppressed it, indicating that regulation of this pathway may be important for Treg-mediated immune control." (PMID 37191720, 2023). "Together, our findings demonstrate that cytosolic serpins provide an inhibitory shield preventing granule protease-induced mast cell apoptosis, and that the granzyme B-Serpinb9a-caspase-3 axis is critical in mast cell survival and could be targeted in the context of allergic diseases." (PMID 34858967, 2021). "In addition, the up-regulation of GZMB expression by histamine in Th2-polarized CD4+ T cells, in CD4+ cells activated by IL-4 or in CD4+ T cells from AD patients indicates that this mediator of allergic inflammation may play a role in the homeostasis of the expression of GMZB in atopy and allergy." (PMID 37470818, 2023).
Arthritis (9 papers, 2014 to 2025). Inflammation of a joint. "The reduced expression of Egr2 coupled with increased T-bet and Granzyme B expression in PD-1high CD4 T cells may serve as one of the molecular signatures for active arthritis." (PMID 32709717, 2020). "In this context it is of note that serum levels of granzyme B, an acidic protease expressed by cytotoxic T lymphocytes, have been reported to be increased in arthritis and positively correlated with erosive RA, and that IL-21 increases its expression in CD8+ T cells." (PMID 26353115, 2015). "DACLIZUMAB is a specific IL2 receptor-targeting drug, which is related to GZMB, IL2RB, and IL2RG, and research indicates its therapeutic potential in the experimental arthritis model induced by CIA." (PMID 38046810, 2023). "Granzyme B specifically cleaves behind aspartic acid residues; cleavage of PAR1 at Arg41 by granzyme B would thus be unlikely, perhaps explaining the lack of a CHIKV arthritis phenotype in GzmB-/- mice." (PMID 28207896, 2017).
osteosarcoma (9 papers, 2020 to 2026). A usually aggressive malignant bone-forming mesenchymal neoplasm, predominantly affecting adolescents and young adults. "Flow cytometry analysis suggested that CD8+ T cell exhibited higher expression levels of IFN-γ and granzyme B when co-cultured with STC2 knockdown osteosarcoma cells compared to those co-cultured with wild-type osteosarcoma cells." (PMID 38229155, 2024). "CD8+ T cells co-cultured with microRNA-200a-overexpressing osteosarcoma cells showed reduced survival, proliferation, and secretion of granzyme B and perforin." (PMID 31981455, 2020). "Moreover, patients with osteosarcoma and a high expression of GZMB have a long overall survival time." (PMID 36204682, 2022). "These cells showed activation and a strong expression of GZMB, GZMA, and IFN-γ, indicating tumor cytotoxicity in osteosarcoma." (PMID 39359731, 2024). "Another interesting case report from Japanese Hiroshima University was the case of extraosseous osteosarcoma with partial spontaneous regression and CD8+T cells, T cell-restricted intracellular antigen-1+ T cells, and granzyme B+ T cells in the tumor mass." (PMID 35720360, 2022). "The expression of Neuronal pentraxin (NPTX2) is negatively correlated with the expression of GZMB and IFNG, Knockdown of NPTX2 in osteosarcoma cells inhibited tumor growth and increased tumor cell apoptosis." (PMID 36204682, 2022). "Furthermore, the two CD8 + cytotoxic clusters demonstrated upregulation of NKG7, GZMB, GZMH, GZMK, CCL3, CCL4, and CCL5, suggesting that chemotherapy amplified the cytotoxic function of CD8 + T cells, potentially enhancing their antitumor activity within the osteosarcoma tumor microenvironment." (PMID 39033089, 2024). "The other subcluster, classified as NK cells, had only a small fraction expressing GZMB, IFN-γ, and PRF1, suggesting a non-activated state in osteosarcoma lesions." (PMID 39359731, 2024).
T-cell lymphoma (9 papers, 2014 to 2025). "The 2 biclonal cases were CD3+ CD56− cells—one of which was granzyme B+ and the other a granzyme B− T-cell lymphoma." (PMID 39319985, 2025). "For NK/T-cell lymphomas, markers like CD2, cytoplasmic CD3, CD56, and cytotoxic granules (granzyme B, perforin, TIA-1) are typically positive." (PMID 41367858, 2025). "Though clonal T-cell receptor gene rearrangement has been reported in 7–38% of extranodal NK/T-cell lymphoma cases, in the absence of CD56, CD8, TIA1, and granzyme B made extranodal NK/T-cell lymphoma, nasal type an unlikely diagnosis." (PMID 25143841, 2014). "The current case demonstrated the immuno characteristics of tumor cells are typical nasal-type NK/T cell lymphoma: CD3+, CD56+, TIA1+, Perforin+, Granzyme B+." (PMID 24886075, 2014). "Based on overall findings, a diagnosis of CD30 and EBV positive T-cell lymphoma primarily involving the subcutaneous tissue was confirmed which could be best classified as PTCL, NOS in terms of the absence of TIA1 and granzyme B expression and the presence of EBV infection." (PMID 25143841, 2014).
asthma (8 papers, 2010 to 2024). "In addition, it was recently shown that NK cell–mediated granzyme B is required for activation of type 2 immune response in a mouse model of asthma." (PMID 37815869, 2023). "Considering these reports, the relationship between increased granzyme B and Campylobacter in our subjects may play a role during asthma exacerbation." (PMID 34667591, 2021). "In conclusion, gram‐negative microbes in the lower airway were related to the acute exacerbation state in children with asthma by increasing inflammatory cytokines such as granzyme B, MIP‐1β, and PD‐L1 and changing the metabolic status such as LPS biosynthesis and glycan degradation." (PMID 34667591, 2021). "Campylobacter was increased significantly according to LEfSe analysis and showed a significant correlation with several inflammatory cytokines including granzyme B, MIP‐1β, and PD‐L1, which were increased in asthma exacerbation." (PMID 34667591, 2021). "Promote allergic sensitization via initiation of type 2 response in OVA-induced asthma; promote pathogenesis via NKG2D and granzyme B in HDM-induced asthma?" (PMID 31293580, 2019).
colon adenocarcinoma (8 papers, 2012 to 2024). "In a syngeneic colon adenocarcinoma tumor model, anti-PD-L1 treatment reinvigorated CD8+ T cells by increasing granzyme B production." (PMID 34944392, 2021). "In addition, the positive correlations between ZC3H12C expression and highly connected CD8+ T genes were also visualized, including CD8A, CD8B, GZMA, GZMB, and PRF1 in colon adenocarcinoma and rectum adenocarcinoma." (PMID 38267865, 2024). "The Cancer Genome Atlas (TCGA)-colon adenocarcinoma (COAD) dataset was also analyzed to identify cytotoxic T lymphocyte (CTL) scores using a set of 5 previously reported genes (CD8A, CD8B, GZMA, GZMB, and PRF1) as a surrogate of tumor infiltrating CD8+ T cells." (PMID 38992029, 2024).
cutaneous melanoma (8 papers, 2021 to 2025). A primary melanoma arising from atypical melanocytes in the skin. "Our recent data also showed that IL4I1 expression is related to a microenvironment enriched in regulatory T cells and poor in granzyme B-positive CD8+ T cells in human primary cutaneous melanoma and is associated with a higher risk of poor outcome in patients." (PMID 37526660, 2023). "Prognostic correlation analysis showed that the GZMB was negatively correlated with survival in BLCA, BRCA, CESC, ovarian serous cystadenocarcinoma (OV), skin cutaneous melanoma (SKCM), UCEC, and uveal melanoma (UVM)." (PMID 34837692, 2021). "In addition, the correlation between IL32 and various genes of cytolytic molecules, such as GZMA, GZMB, and PRF1, is positive, suggesting that IL32 mRNA expression may increase patient survival through the infiltration and activation of anticancer effector cells in cutaneous melanoma." (PMID 34682815, 2021).